BDNF (brain derived neurotrophic factor)
Diseases named in the same sentence as BDNF in open-access papers (continued):
Sharing a sentence is not in itself a finding about the gene and the disease.
depression (continued). "In this study, interactions among miR‐199a‐5p, the WNT pathway, and the CREB1/BDNF axis in the development of depression were investigated." (PMID 34333859, 2021). "It is well established that the BDNF level is different in chronic pain patients and in people who suffer from major depression as compared to HSs." (PMID 33915758, 2021). "Quercetin alleviates LPS-induced depression-like behavior in rats by regulating BDNF-related imbalance of copine 6 and TREM1/2 in the hippocampus and PFC." (PMID 35003290, 2021). "Although the intracerebral administration of BDNF produced an antidepressant-like effect in animal models of depression, clinical use of neurotrophin is limited, mainly due to its suboptimal pharmacokinetic properties and side effects." (PMID 34948177, 2021). "Contrary, HIIE increases peripheral BDNF and attenuates tension, depression, and anger independently of menstrual phase." (PMID 33603039, 2021). "Evidence from animal models shows that stress-induced depression changed the BDNF level via cell signal detection." (PMID 34007290, 2021). "Dysregulated neurogenesis and synaptogenesis have been reported in the brain of patients with major depressive disorders and multiple molecular pathways are believed to be disrupted in these processes, including BDNF, TrkB, PSD95, and SNAP25." (PMID 33526073, 2021). "We found that CPT alleviated the CUS induced depression-related phenotypes by promoting neurogenesis and BDNF/TrkB signaling and inhibiting microglial activation and the release of proinflammatory factors in CUS mice." (PMID 34900345, 2021). "Estrogen deficiency by VCD decreases ChAT, BDNF, and BAG1 and consequently leads to cognitive decline and depression-related behaviors." (PMID 34698102, 2021). "The mRNA and protein expression of BDNF was significantly reduced in the chronic stress‐induced depression model." (PMID 34333865, 2021). "As a result, d-serine-induced changes in BDNF signaling pathway in NAc are involved in mediating depression." (PMID 34654365, 2021). "Because BDNF expression is significantly reduced after the onset of depression, BDNF is considered to be an effective biomarker when stress causes serious brain damage." (PMID 33924992, 2021). "The current findings from animal experiments suggest a novel mechanistic link between IDO1 in the DRN and depression, which the detrimental effects of IDO1 hyperactivity are likely mediated through a loss of hippocampal BDNF expression." (PMID 33591947, 2021). "Considering the role of BDNF in the inhibition of depression, PGC1a/FNDC5/BDNF has been determined to be a critical pathway for neuroprotection; as such, it is expected to be an effective target for therapeutic interventions in depressive disorders." (PMID 34950248, 2021). "In the present study, we found that anxiety-/depression-like behaviors and their related markers BDNF expression and NF-κB activation were more severely fluctuated in the FMTs from patients with IBD/D+ than in ones from patients with IBD/D−." (PMID 34650107, 2021). "This study aims to estimate the contribution of 11 polymorphisms in the genes SLC6A4 (5HTT), HTR1A, HTR2A, HTR1B, SLC6A3 (DAT1), DRD4, DRD2, COMT, and BDNF to suicidal behavior and severity of symptoms of depression and anxiety in the Russian population." (PMID 34199792, 2021). "In the current study, it was revealed that Rb1 treatment enhanced the phosphorylation of AKT and ERK1/2, two downstream regulators of BDNF, in the hippocampus and alleviated depression symptoms in CSDS mice." (PMID 34658847, 2021). "BDNF concentration levels in blood are decreased in depression, bipolar disorder, schizophrenia, anorexia nervosa, and Alzheimer’s disease." (PMID 34640441, 2021). "Our data together are clinically relevant demonstrating the efficacy of WBVT maintaining blood BDNF levels with concomitant improvement in aspects related to biological rhythm (i.e., quality of sleep and depression symptoms)." (PMID 34900203, 2021).
depression (continued). "Based on that translational mechanism, we devote to find a new antidepressant treatment by controlling BDNF in depression." (PMID 32203159, 2021). "The role of BDNF in depression is actively studied and BDNF was the 164th most dysregulated gene in the combined portrait." (PMID 33589676, 2021). "BDNF is downregulated in depression and the BDNF signaling pathway was significantly enriched in the combined portrait." (PMID 33589676, 2021). "MiR‐199a‐5p can target WNT2 to enhance the development of depression through regulation of the CREB/BDNF signaling." (PMID 34333859, 2021). "In order to further verify the depression mouse model at the molecular level, we selected BDNF and CORT as molecular indicators." (PMID 34207497, 2021). "With regard to depression, we know that brain-derived neurotrophic factor (BDNF) is a growth factor, which influences neuronal survival, growth, and neuroplasticity." (PMID 33960267, 2021). "Clinical evidence shows that patients suffering from depression demonstrate decreased BDNF levels in the hippocampus." (PMID 34451801, 2021). "EMO ameliorates chronic unpredictable mild stress (CUMS) induced depression-related behaviors by altering the glucocorticoid receptor (GR) and brain-derived neurotrophic factor (BDNF) levels in the hippocampus." (PMID 34051074, 2021). "Hallmarks of depression include decreased brain BDNF levels and TrkB signaling as well as hippocampal degeneration." (PMID 34743729, 2021). "BDNF is thought to be intimately involved in the pathogenesis of many disorders of the nervous system, including depression." (PMID 34948116, 2021). "Collectively, BHT attenuated CUMS-induced depression-like behavior by regulating BDNF and intestinal flora disorder through the brain-gut axis." (PMID 34475963, 2021). "The common feature between 5‐HT and BDNF is their ability to regulate development and plasticity of neural circuits, involved in mood disorders like depression and anxiety." (PMID 33598202, 2021). "Patients with depression or bipolar disorder have altered hippocampal BDNF expression, and patients with depression or PTSD have reduced hippocampal volume." (PMID 33572375, 2021). "Research on the peripheral concentration of BDNF in patients suffering from depression has been conducted since the beginning of this century." (PMID 33809367, 2021). "The serum BDNF levels of depression patients also were negatively correlated with the degree of depression, when the data from the two trials were collapsed." (PMID 34776888, 2021). "Decreased bradykinin is thought to reduce brain-derived neurotrophic factor release, inhibit synaptogenesis, and enhance the progression of depression." (PMID 34708129, 2021). "It was recently demonstrated that 7,8-dihydroxyflavone (7,8-DHF), a novel stroke medication permeable to the membrane and able to cross the blood–brain barrier (BBB), acts as a BDNF mimetic to reduce depression-like behavior in mice and rats." (PMID 34959450, 2021). "In patients with depression, abnormal expression of miRNA-34a and miR-451-a significantly lower the expression of BDNF which affects indirectly on integration of 5HT and COR systems via producing a pro-neuroprotection signaling cascades." (PMID 34721735, 2021). "This protein is a widely expressed neurotrophin serving several functions within the CNS, including neuronal differentiation and survival, and regulation of BDNF concentration is involved in depression and anxiety." (PMID 34356624, 2021). "Collectively, our observations indicate that RVG/siPdcd4 effectively rescues CRS-induced neuronal atrophy and depression behavior via promoting BDNF expression." (PMID 34772918, 2021). "Changes in the activity of various signaling processes such as BDNF, NMDA, and mammalian target of rapamycin (mTOR) are possible mechanisms that underlie alterations of synaptic plasticity leading to depression." (PMID 34064233, 2021).
depression (continued). "MS decreased hippocampal BDNF and p-AKT/AKT levels and was associated with depression-like behavior, while an enriched environment reversed this negative impact and upregulated the PI3K-AKT pathway." (PMID 34890365, 2021). "Recently, considerable efforts have been made in regulating the expression of BDNF for therapeutic applications in depression." (PMID 34772918, 2021). "Lower baseline BDNF levels observed in patients possibly confirm an impairment of the stress-adaptation system and neuroplasticity in depression." (PMID 34362162, 2021). "Studies have shown that BDNF expression is downregulated in patients with depression and that antidepressant drugs can increase the level of BDNF expression." (PMID 35194435, 2021). "In this study, we estimated the contribution of SLC6A4 (5HTT), HTR1A, HTR2A, HTR1B, SLC6A3 (DAT1), DRD4, DRD2, COMT, and BDNF genes to the suicidal behavior and severity of symptoms of depression and anxiety in the East-Slavic population of Russia." (PMID 34199792, 2021). "Several low-molecular-weight peptide and non-peptide compounds with favorable pharmacokinetic profiles acting on the BDNF/TrkB pathway and exerting antidepressant properties in various depression-like animal behavioral models have been developed to date." (PMID 34948177, 2021). "A recent study also found that circulatory BDNF was decreased in patients with type 2 diabetes and depression." (PMID 33477900, 2021). "Anthocyanin showed beneficial effects in depression by increasing neurotransmitter monoamine and brain-derived neurotrophic factor (BDNF) expression up-regulation." (PMID 34944391, 2021). "It is proven that the BDNF-TrkB pathway plays a critical role in the occurrence of mental illnesses, such as depression and anxiety." (PMID 34959450, 2021). "Most interestingly, one recent study found that the impact of BDNF serum levels on the course of late-life depression was conditional on the presence of both the use of SSRIs and a history of childhood trauma." (PMID 33643008, 2021). "Herein, for the first time, we analyzed the levels of NP, neurotransmitters, and brain-derived neurotrophic factor (BDNF) in patients with depression through a hospital-based case control study." (PMID 34046258, 2021). "Previous studies have reported that oral administration of MOOs can increase the monoamine and BDNF levels in rodent depression models, which suggests its effect on depression." (PMID 34559953, 2021). "It has been reported that the deletion of TrkB in mice caused a significant reduction in behavioural evidence for epileptogenesis, and BDNF and TrkB expression increased in the amygdala of rats with epilepsy and depression." (PMID 34899313, 2021). "Our data indicate that transcription factor Cc2d1a/Freud-1 is implicated in the pathogenesis of depressive disorders not only via the 5-HT1A receptor and transcription factor CREB but also through an influence on BDNF." (PMID 34948116, 2021). "Here, we reviewed various biomarkers, including cytokines, BDNF, neurohormones, GI biomarkers, and oxidative stress indices specifically studied for childhood and adolescent depressive disorders." (PMID 34576215, 2021). "These assumptions are consistent with evidence of a positive (therapeutic) effect of 5-HT1A receptor activation by antidepressants (e.g., vilazodone) on the BDNF level in depressive disorders." (PMID 34948116, 2021). "For example, Kir 4.1, which can regulate spatial K+ buffering and BDNF expression in astrocytes, contributes to the modulation of epilepsy, chronic pain, and depressive disorders." (PMID 34803603, 2021). "Changes in levels of BDNF in the serum of patients with depressive disorders emphasize the potential of BDNF as a biomarker." (PMID 33673282, 2021). "In the past two decades, BDNF has been widely studied in the context of neuropsychiatric disorders especially for depressive disorders, bipolar disorder, schizophrenia, addiction, and eating disorders." (PMID 34950248, 2021).
depression (continued). "Patients with depressive disorders have significantly lower concentrations of BDNF in their blood and interestingly, after antidepressant treatments, BDNF concentrations were back to physiological concentrations." (PMID 34539633, 2021). "Our findings suggest the potential involvement of thromboxane and brain-derived neurotrophic factor (BDNF) in the pathophysiology of depressive disorder in children and adolescents." (PMID 33801688, 2021). "Accordingly, BDNF infusion produces anti-depressive-like effects in the mouse midbrain of depression mice models." (PMID 34833132, 2021). "This lack of association indicates that rs6265 is related to a pathogenetic element contributing to the vulnerability of becoming severely depressed and less to mediating the actual severity of this depression (by modulating actual BDNF expression)." (PMID 32116853, 2020). "Clinical studies have shown that plasma BDNF levels are reduced in patients with depression, and antidepressant treatment can increase BDNF levels." (PMID 33293948, 2020). "The use of an antidepressant will increase BDNF, regenerate brain cells, and reduce oxidative stress, depression, and anxiety." (PMID 33014278, 2020). "In in vivo or in vitro rat experiments, miR-206 has been proven to be an important regulator and participator in depression via its direct target gene BDNF." (PMID 33029119, 2020). "This suggests a different and complex modulation of BDNF-specific promoters in female and male subjects with depression, however, the particular modifications of these promoters activity needs further investigation." (PMID 32532322, 2020). "In this regard, BDNF appears to have a strong mediating role in both long-term potentiation and long-term depression, as well as in influencing broader morphological changes in neurons, likely by signalling changes in actin to effect remodelling." (PMID 32218234, 2020). "Consistent with previous studies, this study shows that the levels of plasma BDNF and hippocampal BDNF mRNA and protein were lowed in CUS rats with depression‐like behaviors, while escitalopram normalized the BDNF expression in the hippocampus." (PMID 32307916, 2020). "Proinflammatory cytokines can reduce the expression of BDNF, and neurotrophic factors are critical in the pathogenesis of depression and brain neuroplasticity." (PMID 32184729, 2020). "On the contrary, the upregulation of miR-182 can reduce the target BDNF levels and exacerbate depression-like phenotypes." (PMID 32085670, 2020). "In fact, the pro-inflammatory microglial cell is related to low BDNF brain levels in an LPS-induced depression-like model." (PMID 33322180, 2020). "The detrimental effect of depression on cognitive functioning was moderated by two factors known to alter BDNF function the brain: BDNF Val66Met genotype and physical exercise." (PMID 33362593, 2020). "Some papers excluded subjects with depression to dismiss the potential effect of this disorder on the BDNF level." (PMID 33152026, 2020). "In this study, we showed that the BDNF-FoxO1 axis in the mPFC is important for regulating depression-related behavior in postpartum female mice." (PMID 32532322, 2020). "Ongoing studies in our laboratory are assessing the role of BDNF signaling in GWI depression and its alteration following KET administration in GWI rats." (PMID 32629972, 2020). "There is a growing body of evidence that abnormalities in the BDNF system are involved in the pathophysiology of late-life depression." (PMID 33269104, 2020). "Chronic i.c.v. infusion of 2 μg apelin-13 upregulated the brain-derived neurotrophic factor (BDNF) against chronic stress-induced depression-like phenotypes by ameliorating HPA axis and hippocampal glucocorticoid receptor dysfunctions." (PMID 32231577, 2020). "PAI-1 participates in the hydrolysis of brain-derived neurotrophic factor (BDNF) to regulate the growth and apoptosis of neurons, which are thought to be associated with depression." (PMID 32901686, 2020).
depression (continued). "Regulated by hormone signaling pathway, calcium signaling pathway, and stress-induced signaling pathway, CREB is phosphorylated and regulates the expression of BDNF, which plays a key role in neuroprotective and neurotrophic processes related to depression." (PMID 33569009, 2020). "Candidate genes of DNA methylation, such as NR3C1, SLC6A4, and BDNF, have been regarded as potential biomarkers of depression." (PMID 32256396, 2020). "The well-known link of BDNF with depression has led to its frequent use as a potential biomarker in psychiatric disorders." (PMID 32102680, 2020). "Here, we presented the contribution of altered BDNF signaling in the pathophysiology of brain diseases, including mental disorders (i.e., depression), neurodegenerative diseases, (i.e., Alzheimer’s disease), and brain tumor (i.e., glioblastoma)." (PMID 33096634, 2020). "BDNF regulates synaptogenesis and survival of adult neurons, enhances the mechanism of synaptic plasticity, thereby influencing cognition, and preventing depression and Alzheimer’s disease." (PMID 33192480, 2020). "Treatment with AC extract ameliorates depression-like behavioral symptoms and restores BDNF and TrkB expression." (PMID 33109198, 2020). "For instance, brain-derived neurotrophic factor (BDNF) has been proposed to play a major role in the pathophysiology of depression, and has also been related to AUD." (PMID 32372985, 2020). "Deficits in BDNF signaling are reported to contribute to the pathogenesis of several major diseases, such as Huntington’s disease, Alzheimer’s disease (AD), depression, schizophrenia, bipolar, and anxiety disorders." (PMID 33096634, 2020). "To help clarify this issue, here we evaluated the relationship between sleep quality and disturbances, salivary CAR, and serum BDNF levels in patients with treatment-resistant major depression, compared with healthy volunteers." (PMID 32410966, 2020). "Consistently, Huanglian-Jie-Du-Tang extract ameliorates depression-like behaviors via BDNF-TrkB-CREB Pathway." (PMID 33265983, 2020). "Impaired levels of BDNF have been widely studied in the context of stress-related psychiatric outcomes like major depression and anxiety disorders, both in animal models and human studies." (PMID 33077716, 2020). "Other microRNAs, such as miR-10b and miR-16, which can directly regulate BDNF levels, have been reported to participate in stress-induced anxiety- and depression-like behaviors of rats." (PMID 32085670, 2020). "In particular, decreased BDNF levels and impaired neuroplasticity in the hippocampus, prefrontal cortex, and amygdala have been demonstrated in rodent models of depression." (PMID 32992988, 2020). "In humans, patients with major depressive disorder (MDD) showed reduced levels of BDNF transcripts in the prefrontal cortex." (PMID 32085670, 2020). "A decrease in BDNF levels in the blood and brain was observed in patients with depression or suffering from PD and AD." (PMID 32050617, 2020). "Here, we show that PEA exerts antidepressant effects by modulating the Brain-derived neurotrophic factor (BDNF)/tropomyosin receptor kinase B (TrkB)/cAMP response element binding protein (CREB) signaling pathway in CORT-induced depression." (PMID 33265983, 2020). "The major biomarkers BDNF, Bcl-2, and Bax are regulated by stress and depression, and BDNF exerts a neuroprotective effect by regulating members of the Bcl-2 family." (PMID 33256231, 2020). "In this study, we explored the relationship between common and rare functional variation in the BDNF gene in young people with depression as an early onset subtype of depression using next‐generation sequencing." (PMID 32869548, 2020). "Previous studies have reported that fibroblast growth factor 21 (FGF21), β-klotho, mature brain-derived neurotrophic factor (mBDNF), and BDNF precursor (proBDNF) play important roles in the pathogenesis and treatment of coronary heart disease and depression." (PMID 33584362, 2020).